IL6 (interleukin 6)
Diseases named in the same sentence as IL6 in open-access papers (continued):
Sharing a sentence is not in itself a finding about the gene and the disease.
nephritis (continued). "Moreover, IL-6, IL-8 and IL-10 concentrations could accurately identify patients with nephritis (IL-6: AUC = 0.88, CI = 0.76–0.99, p = 0.0002; IL-8: AUC = 0.85, CI = 0.73–0.97, p = 0.0002; IL-10: AUC = 0.73, CI = 0.56–0.89, p = 0.02)." (PMID 29190714, 2017). "In addition to the systemic effects, IL-6 may act locally as demonstrated by the presence of IL-6 in the cerebrospinal fluid in patients with neuropsychiatric involvement, and in urine in patients with nephritis." (PMID 28380214, 2017). "The protective influence of XMU-MP-1 towards renal MQC resulted in smooth mitochondria/autophagy flux and ameliorated kidney inflammation, as evidenced by decreased protein expression of LC3B-II, p62 and IL6." (PMID 39608245, 2024). "The correlation analysis between nephritis and different concentrations of cytokines showed that the levels of IL-6 (r = 0.368, P = 0.035) and TNF-α (r = 0.415, P = 0.031) were positively correlated with the occurrence of nephritis." (PMID 33882880, 2021). "Urinary markers of kidney inflammation, i.e., AGP and IL-6 were noticed to be significantly elevated in the rats of the control diabetic group, and EMP efficiently decreased their levels in the urine." (PMID 31168342, 2019). "Rat Thy-1N was reproduced and then the mRNA and/or protein levels of C5a, IL-6 and TNF-α in the rat renal tissues were detected at different time points after the nephritis induction." (PMID 27583546, 2016). "IL-1β, either directly or through the induction of other cytokines such as IL-6 and TNF-α, promotes the development of kidney inflammation by increasing the expression of adhesion molecules and chemotactic factors and by recruiting inflammatory cells, thereby inducing kidney injury." (PMID 39117988, 2025). "This study has demonstrated that high-dose CS-DMY-NPs significantly regulated the release of IL-1β, TNF-α, and IL-6 in the kidneys of mice, suggesting that DMY may attenuate LPS-induced acute kidney inflammation injury." (PMID 39330225, 2024). "Furthermore, data from earlier studies indicated that therapy with WS significantly inhibited nephritis, proteinuria, TNF-α, IL-6, and ROS." (PMID 39502378, 2024). "Anti-IL-6 antibody not only did not improve nephritis but also did not suppress the production of anti-GBM antibody." (PMID 38004064, 2023). "Besides, serum level of HOTAIR had a significantly positive correlation with IL-6 (r = 0.675, P<0.0001), MMP-9 level (r = 0.757, P<0.0001), proteinuria (r = 0.287, P = 0.035) and grades of nephritis (r = 0.296, P = 0.024)." (PMID 35972968, 2022). "Furthermore, HOTAIR expression level had significantly positive correlation with IL-6 (r = 0.578, P<0.0001), MMP-9 level (r = 0.762, P<0.0001), nephritis grades (r = 0.296, P = 0.024) and proteinuria (r = 0.287, P = 0.035)." (PMID 35972968, 2022). "Concerning pro-inflammatory cytokines, we found elevated levels of IL-1β, IL-6 and IL-8 in the serum of all patients, with or without nephritis, compared to the controls." (PMID 29190714, 2017). "Interferon-γ, interleukin-6, and interleukin-12 levels were significantly increased in plasma from patients with SLE with active nephritis (AN), as compared to both patients with SLE with inactive nephritis (IN) and the control group." (PMID 29208022, 2017). "Besides, the patients with nephritis were in the inflammatory status, and inflammation acted as an influencing factor has been clarified by many studies, which found that Scys-C was associated with many inflammatory markers like IL-6, TNF-α but not with C-reactive protein (CRP)." (PMID 24465871, 2014). "Top pathways included IL6-Signaling (p-value < 2.9e-25) and ERK/MAPK cascade (p-value < 4.85E-11).Although multiple signaling pathways were predicted for the miRNAs from both profiling platforms, the main toxicology related function was ‘Nephritis’." (PMID 24942259, 2014).
nephritis (continued). "Reactive free radical species–mediated oxidative stress may lead to the infiltration of inflammatory cells and increase the mRNA expression of inflammatory genes such as TNF-α, IL-6, NF-кB, and TGF-β, which are all participate in the progression of kidney inflammation in 2K1C rats." (PMID 39886537, 2025). "However, the levels of IL-6 (P < 0.05) and IFN- γ (P < 0.05) were still negatively correlated with CD4+/CD8+, and the concentration of IL-6 (P < 0.05) was still positively correlated with the occurrence of nephritis." (PMID 33882880, 2021). "Urine IL-6, IL-8, and IL-10 concentrations distinguished IgAV with or without nephritis." (PMID 29190714, 2017). "As nephritis progresses, the SGLT2 accumulates without being metabolized due to renal dysfunction and proinflammatory cytokines like IL-6 and TNF-α induce SGLT2 expression in diabetic kidneys." (PMID 34425759, 2021). "The gene expression levels of TNF-α, IL-1β, MCP-1, and IL-6, which are known as proinflammatory cytokines, were much higher in the WKY-HBSS rats than in WKY rats without nephritis." (PMID 23826305, 2013).
thyroid cancer (55 papers, 2013 to 2026). "The published researches reported that IL-6 expression is higher in patients with benign and malignant thyroid neoplasms than healthy controls, and it is associated with tumor aggressiveness and poor survival." (PMID 32655554, 2020). "In summary, our meta-analysis suggests that adipokines, including TNF-α, IL-6 and leptin are associated with thyroid carcinoma." (PMID 32819324, 2020). "To elucidate the mechanism underlying the effects of IL‐6 in thyroid cancer, we assessed the expression of its downstream genes." (PMID 31631580, 2019). "Genotypic frequencies and association of the IL6-174 SNP with thyroid carcinoma and basal cell carcinoma (adjusted for gender an age)." (PMID 27662210, 2016). "We assessed the association of the IL6-174 G>C SNP with LDR effects such as thyroid carcinoma, basal cell carcinoma and carotid atherosclerosis in the Portuguese tinea capitis cohort." (PMID 27662210, 2016). "A link between thyroid cancer and inflammation has also been recognized; thyroid carcinomas are associated with the constitutive expression of several proinflammatory cytokines (IL-8, IL-6, GROα, IL-1α, G-CSF, GM-CSF) that can be able to maintain the invasive phenotype." (PMID 25268744, 2014). "Furthermore, recently, a role of activated interleukin 6 (IL-6)/STAT3 signalling has been reported in driving the resistance of BRAF-mutated thyroid cancer cells to vemurafenib, and the blockade of the IL-6 or STAT3 axis has been proposed to increase vemurafenib activity." (PMID 36979673, 2023). "Current research indicates that serum IL‐6 levels are significantly elevated in individuals with malignant thyroid tumors compared to healthy controls." (PMID 40620232, 2025). "In a co-culture test on TC, soluble molecules including ROS and IL-6 released by undifferentiated thyroid cancer cells were discovered to transform fibroblasts into CAF via modulating the Src/Akt signaling pathway in fibroblasts." (PMID 39776907, 2024). "Many studies have shown that higher increased levels of IL-6 and CRP, which results in increased FT3 and TT4 levels and increased risk of thyroid carcinoma." (PMID 39764244, 2024). "To study how UHRF1 promoted thyroid cancer cell metastasis, we analyzed the transcription levels of key regulators of immunoregulatory cytokine interleukin 6 (IL-6) and the macrophage migration inhibitory factor (MIF) in BCPAP by qPCR." (PMID 35996525, 2022). "Other studies also confirmed significant positive associations between levels of IL-6 and CRP and thyroid cancer based on a larger population." (PMID 34684331, 2021). "In general, the data above support that IL-6 is important for thyroid cancer, but the detail mechanism remain to be further study." (PMID 32819324, 2020). "For in vitro research, IL-6 was also found to be expressed in thyroid cancer cell lines and a potential role of IL-6 in PTC was confirmed indirectly." (PMID 32819324, 2020). "Previous studies showed that IL-6 expression was significantly down-regulated in undifferentiated thyroid cancer tissues." (PMID 32655554, 2020). "Serum IL-6 level in thyroid cancer has been evaluated in numerous studies including in vivo and in vitro studies." (PMID 32819324, 2020). "Among the 30 included studies, 9 reported the level of serum IL-6 in patients with thyroid carcinoma and control subjects." (PMID 32819324, 2020). "Adipokines (TNF-α, IL-6 and leptin) show a strong relationship between elevated concentrations (in serum and/or tissue) and thyroid carcinoma." (PMID 32819324, 2020). "The serum interleukin-6 (IL-6) in patients with thyroid carcinoma is higher than that in control (SMD = 1.04, 95% CI: 0.40 to 1.67, I2 = 96%, P = 0.001)." (PMID 32819324, 2020). "We did observe that the IL6 gene expression was enhanced in FTC-133 thyroid cancer cells, which remained adherent for 24 h on the RPM." (PMID 30545079, 2018).
thyroid cancer (continued). "In summary, the cytokines IL-6 and IL-8 are involved in migration and growth in thyroid cancer, and both are sensitive to altered gravity conditions." (PMID 30545079, 2018). "This is the first report on 15d-PGJ2-induced SOCS3 expression, which evidences a novel therapeutic option for the treatment of thyroid cancer and other cancers that are dependent on IL-6 signaling." (PMID 27190500, 2016). "From the present study, it can be evident that IL-6 has a significant role in thyroid cancer progression and targeting IL-6 signalling can be helpful in clinical management of thyroid carcinoma patients with more aggressive tumour characteristics." (PMID 27034885, 2016). "To evaluate the possible role of the cytokines IL-6 and IL-8 for the expression of selected proteins in thyroid cancer cells, we studied the impact of IL-6 and IL-8 application on Ki-67, ß1-integrin, talin-1, and beta-actin proteins in adherent ML-1 cells." (PMID 26274317, 2015). "We did previously observe that IL6 gene expression was enhanced in FTC-133 thyroid cancer cells, which remained adherent for 24 hours on the RPM." (PMID 23844163, 2013). "For in vitro studies, IL‐6 was also found to be expressed in thyroid cancer." (PMID 40620232, 2025). "In thyroid cancer, this protein has been reported as a potential diagnostic and prognostic biomarker of PTC by regulating epithelial-mesenchymal transition and activating the IL-6/JAK2/STAT3 pathway." (PMID 37833989, 2023). "Notably, HHV-6A infection very strongly stimulated the release of IL-6, which can be also considered a growth factor for thyroid cancer stem cells and which has been shown to sustain thyroid cancer progression." (PMID 37896899, 2023). "As a consequence, CAFs may shift phenotype and function by secreting IL-6 and ROS and thereby increase the aggressiveness of thyroid carcinoma." (PMID 37345200, 2023). "Moreover, MCs release TNF- α, IL-6, IL-8, and other cytokines to facilitate the proliferation and invasion of carcinoma cells, thereby stimulating the development and spread of thyroid carcinoma." (PMID 37345200, 2023). "IL-6 and TGFβ appeared to impact thyroid cancer tumorigenesis." (PMID 36551653, 2022). "Currently, the role of IL-6 in thyroid cancer remains controversial." (PMID 35634509, 2022). "TFF3 inhibits thyroid cancer cell progression related to IL-6/JAK/STAT3 signaling pathway." (PMID 34567204, 2021). "Then, STAT3-activated M2 macrophages overexpressing IL-6 would promote thyroid cancer progression." (PMID 34638305, 2021). "The IL-6/JAK/STAT3 signaling pathway might be involved in the effect of TFF3 on thyroid cancer cell progression." (PMID 34567204, 2021). "Moreover, autocrine interleukin-6 (IL-6) secretion contributes to BRAF-resistance in thyroid cancer cells through the induction of JAK/STAT3 and MAPK signalling." (PMID 34204950, 2021). "IL-6 is negatively correlated to aggressiveness of thyroid cancer." (PMID 32655554, 2020). "However, it needs more clinical data to verify the relationship between the expression of IL-6 and thyroid carcinoma tissue." (PMID 32819324, 2020). "By contrast, IL6/STAT3 axis mediated resistance to BRAF inhibitors in thyroid carcinoma cells." (PMID 32851683, 2020). "In summary, these results support the hypothesis that simulated microgravity using the RPM or the CLINO favors 3D growth of thyroid cancer cells and that IL-6 plays an important role in this process." (PMID 26274317, 2015). "Therefore, chronic inflammation in the context of Hashimoto’s thyroiditis, an abnormal immune microenvironment caused by elevated IL-6, and decreased CD8+ T cell function may jointly lead to the coexistence of thyroid cancer and PCNSL." (PMID 39727679, 2024).
thyroid cancer (continued). "Furthermore, it has been reported that human fibroblasts activated by thyroid-cancer-cell-secreted factors significantly enhance the expression and secretion of interleukin 6 (IL-6), which is an inflammatory cytokine involved in the progression of several types of cancer, including thyroid tumors." (PMID 36077709, 2022). "In addition to ROS and IL-6, thyroid cancer cells secrete great amounts of platelet-derived growth factor (PDGF), which could serve as a causative molecule promoting fibroblast activation and CAF formation." (PMID 36077709, 2022). "IL6, an important cytokine, has been shown to mediate diverse biological functions including normal cellular growth and immune response through activation of STAT3 while its aberrant secretion is known to associated with the pathogenesis of various human diseases including thyroid cancer." (PMID 31936675, 2020). "Thus, the level of serum IL-6 is higher in patients with thyroid carcinoma." (PMID 32819324, 2020). "Finally in conclusion, IL-6 has an important role in thyroid cancer progression." (PMID 27034885, 2016). "Thus targeting IL-6 signalling can help in clinical management of thyroid carcinoma patients." (PMID 27034885, 2016). "We have further evaluated the IL-6 and TNF-α cytokine release in the culture supernatants of 48 h drug-treated K1 thyroid cancer cells." (PMID 41150811, 2025). "In thyroid cancer, low expression of TFF3 can increase cell proliferation, migration, and invasion via activation of the IL-6/JAK/STAT3 signaling pathway." (PMID 38745021, 2024). "Furthermore, ER stress induces high expression of IL-6 and IL-8 to mediate radioiodine resistance in thyroid cancer cells; curcumin as well as the molecularly targeted drug sorafenib can inhibit ER stress to reduce the resistance of thyroid cancer cells to radioiodine." (PMID 37484013, 2023). "Histamine, IL-6, IL-1, TNF-α, and chemokines such as CXCL1/GRO-α, CXCL8/IL-8, and CXCL10/IP-10 are secreted from mast cells when thyroid cancer cells are activated." (PMID 36293435, 2022). "Leptin can increase the expression of VEGF, interleukin-6 (IL-6), and tumor necrosis factor-α (TNF-α) to promote progression and metastasis of thyroid cancer." (PMID 33194342, 2020). "In previous studies, the analysis of adiponectin and thyroid cancer mostly focused on TNF-, IL-6, Leptin and Adiponectin." (PMID 32819324, 2020). "The signalling elements IL-6, IL-8, OPN, TLN1 and CTGF were involved together with NF-κB p65 in the RPM-dependent thyroid carcinoma cell MCS formation." (PMID 31137658, 2019). "Tumor-related leukocytosis caused by the release of cytokines such as granulocyte colony-stimulating factor (g-csf), granulocyte-macrophage colony-stimulating factor (gm-CSF), IL-1a,b, IL-3, IL-6, and TNF-α and its prognostic effect have been described in various cancers, including thyroid cancers." (PMID 40004836, 2025). "Similarly, in lung cancer, the overexpression of ANXA8 activates the EGFR/AKT/mTOR signalling pathway to promote proliferation, while in thyroid cancer, increased ANXA1 promotes thyroid cancer proliferation by mediating IL-6/JAK2/STAT3." (PMID 36936694, 2023). "In addition, high levels of serum tumor necrosis factor-alpha (TNF-α), interleukin-6, TNF-α immunoreactivity, and leptin hormone in thyroid tissues have been demonstrated in patients with thyroid cancer." (PMID 36230635, 2022). "Our results suggest that UHRF1 could induce the metastasis of thyroid cancer, and the potential signaling pathway might be that UHRF1 activates c-Jun/AP-1 to increase the expression of IL-6 and MIF." (PMID 35996525, 2022). "Based on these studies, the signaling pathway that UHRF1 plus c-Jun/AP-1 increased the expression of IL-6 and MIF might be a potential key mechanism of thyroid cancer metastasis." (PMID 35996525, 2022). "Two studies reported the ratio of IL-6 immunoreactivity both in thyroid carcinoma tissue and non-carcinoma tissue." (PMID 32819324, 2020).
thyroid cancer (continued). "In summary, these data suggest that nevirapine has inhibitory effects in human dedifferentiated thyroid cancer by targeting the IL‐6/STAT3 signaling pathway, and our findings demonstrate that nevirapine may be useful as a therapy against human thyroid cancer." (PMID 31631580, 2019). "IL-6 is known to be involved in angiogenesis and metastasis not only in thyroid cancer but also in several other cancer types." (PMID 31137658, 2019). "This is because on the one hand, it could secrete histamine, CXCL1/GRO-α and CXCL10/IP-10 to promote the proliferation of thyroid cancer cells, and on the other hand, it could initiate EMT by secreting TNF, IL-6 and CXCL8/IL-8, which were essential in EMT process." (PMID 36568979, 2022). "However, other studies show a different result that no significance different of IL-6 was found between thyroid cancer and non-thyroid cancer." (PMID 32819324, 2020). "The pooled OR of the limited two studies do not show an increased ratio of IL-6 immunoreactivity in thyroid carcinoma tissues (OR = 1.23 (95% CI 0.62 to 2.43, P = 0.55)) and a large heterogeneity always exists (heterogeneity test, Chi2 = 7.16, P = 0.007, I2 = 86%)." (PMID 32819324, 2020).